NRG1 (neuregulin 1)
Diseases named in the same sentence as NRG1 in open-access papers (continued):
Sharing a sentence is not in itself a finding about the gene and the disease.
tumor (continued). "However, simultaneous high expression of HER3 and NRG1 within the tumor (percentages of positive neoplastic cells were more than the mean value of corresponding markers) was significantly associated with the presence of metastasis and high cancer staging, and the presence of local recurrence." (PMID 34465724, 2021). "Thus, we consider that dual targeting of NRG1 and HAS2 may be an interesting treatment strategy applicable for tumours with high expression of NRG1." (PMID 33692466, 2021). "NRG1 is released in the tumor endothelium and may have a tumor protecting effect." (PMID 30836676, 2019). "In addition, we suggest new potential tumor-specific biomarkers that may improve on using NRG1 alone and allow for selection of a subset of HNSCC patients for the combination of KTN3379 with EGFR inhibitors." (PMID 28723928, 2017). "Ideally, we would have liked to determine whether NRG1 is cleaved in the absence of Trop2 in tumor samples, but cleavage specific antibodies are not available and the multiple variant isoforms of NRG1 exist further making such an approach ambiguous." (PMID 25238142, 2014). "Thus, in vitro investigation using tumor cell lines treated with Nrg1 may provide more insight into its roles in endocrine organ specific functions." (PMID 24348587, 2013). "Tumours with SDC4::NRG1 fusions also overexpress HER2 pathway-related genes, reinforcing NRG1-driven activation." (PMID 41914575, 2026). "Damage to axons induces the release of factors like neuregulin 1 (NRG1), which activates Schwann cells to proliferate and migrate, creating pathways for tumor cells." (PMID 40909268, 2025). "Fib-BMP5 was found mainly in the tumour samples, and was characterized by the elevated expression of SLC14A1, NRG1, and WNT5A." (PMID 41281745, 2025). "NRG1 promotes androgen resistance and CRPC progression through multiple mechanisms, including bypassing AR signaling and modulating the tumor microenvironment." (PMID 40740239, 2025). "NRG1_ERBB4 activates the YAP transcriptional coactivator, promoting cell growth and migration via the Hippo pathway and contributing to tumor aggressiveness." (PMID 40969325, 2025). "Across multiple tumor types, stroma-derived neuregulin-1 (NRG1) can activate HER3 via paracrine signaling, thereby promoting tumor-cell survival and therapy resistance under treatment pressure." (PMID 41514658, 2025). "Silencing NRG1 expression in tumor cells disrupts important signaling pathways, such as PI3K/AKT, and leads to inhibition of tumor cell growth and migration." (PMID 41439026, 2025). "To further validate the roles of NRG1 and PDGFC in promoting PTX resistance in BC in vivo, we established ectopic tumor models using nude mice." (PMID 41213930, 2025). "During epithelial-mesenchymal transition (EMT), NRG1 regulates transcription factors like ZEB1, enhancing tumor cell migration and invasion, which are key drivers of CRPC metastasis and resistance." (PMID 40740239, 2025). "They promote tumor growth by remodeling the ECM to facilitate invasion, secreting pro-tumorigenic factors such as IL-6 and neuregulin 1 (NRG1) that enhance proliferation and therapy resistance, as well as fostering an immunosuppressive “cold” microenvironment." (PMID 41228234, 2025). "In BNST patients, high expression of NRG1 activates the PI3K/AKT signaling pathway, recruiting M2 macrophages to the tumor site and accelerating tumor progression." (PMID 38331905, 2024). "Other compensatory pathways can also contribute to tumor growth in certain contexts, for example BTK-C was identified as a survival factor and was involved in NRG1-mediated drug resistance in HER2+ BC cells." (PMID 38360930, 2024). "Drugs targeting the binding of NRG1 to ERBB3 and/or the heterodimerization of ERBB2/ERBB3, such as the bispecific monoclonal antibody zenocutuzumab, have demonstrated tumor volume reduction inNRG1fusion-positive tumors." (PMID 38414979, 2024).
tumor (continued). "The results are consistent with the previous bioinformatics analysis, indicating a positive correlation between the high expression of NRG1 in BNST and the aggregation of M2 macrophages in the tumor site while being negatively correlated with neutrophils." (PMID 38331905, 2024). "In the NRG1-high expression scenario, our model predicts that it greatly diminishes the TKI-mediated tumor growth inhibition." (PMID 38360930, 2024). "The results showed that knocking down NRG1 not only resulted in a decrease in the expression levels of critical proteins in the PI3K signaling pathway but also weakened tumor growth ability, leading to an extension of the survival time of mice." (PMID 38331905, 2024). "In conclusion, these results demonstrate that NRG1 maintains the characteristics and malignant behavior of BNST tumor cells through the PI3K/AKT signaling pathway." (PMID 38331905, 2024). "To demonstrate the close relationship between the influence of NRG1 on the BNST microenvironment and the activation of the PI3K/AKT pathway, we treated mice with a PI3K signaling inhibitor during tumor formation." (PMID 38331905, 2024). "We investigated tumor cell proliferation as well as the cellular and molecular mechanisms of tamoxifen, abemaciclib, AMG232, and NRG1 treatments as a function of HER4 in vitro." (PMID 39000582, 2024). "Ratio differences of important immune-related AS events (clualt3p199530 NRG1, clualt5p154454 SH3BP2, clualt5p114936 ACKR3, clualt5p152292 IL15, cluir97910 NFKBIB, and clualt5p204621 IKBKG) between tumor and normal tissues are presented." (PMID 37139238, 2023). "Following blockade of the NeuReGulin-1/human epidermal growth factor receptor-3 (NRG1/HER3) axis using antibodies, tumours were resensitized to antiandrogen therapy." (PMID 37537666, 2023). "In addition, EGFR exon 20 insertions, Erb-B2 receptor tyrosine kinase 2 (ERBB2) mutations, neuregulin 1 (NRG1) fusions, KRAS proto-oncogene (KRAS) G12C, and tumor mutational burden (TMB) are evolving targeting/biomarkers and may eventually be included in the test panels, if possible." (PMID 37371816, 2023). "To demonstrate solidarity of our observations, we investigated the relevance of NRG1 expression in the response to radiotherapy and prognosis of CSCC patients in cohort 3 (91 tumor specimens from 59 patients)." (PMID 37424047, 2023). "The researchers found that the combination therapy inhibited the NRG1/HER3-signaling pathway and ultimately resulted in more tumor inhibition and prolonged tumor regression." (PMID 37298631, 2023). "In tumor specimens from responders, we observed smaller numbers of IER3+ CAFs and NRG1+ malignant cells in randomly selected fields and a dispersed distribution pattern of IER3+ CAFs inside tumor bed." (PMID 37424047, 2023). "Among them, TDGF1, and GRP were up-regulated in tumor samples, while NRG1, CRLF1, and IL20RB were down-regulated in tumor samples." (PMID 35748788, 2022). "The mean and standard deviation of the percentage of positive tumor cells was 72.93 ± 31.68% for HER3 and 81.65 ± 21.84% for NRG1, respectively." (PMID 34465724, 2021). "In these scenarios, TNC is functioned as a strong promoter, leading to activation of oncogenes NRG1 and USP6, and subsequently induction of tumor formation." (PMID 34256767, 2021). "Directly silencing of either MUC1 or NRG1 by siRNA significantly inhibited NSCLC cell growth and tumour formation in vitro and in vivo, implying that they can be used as potential therapeutic targets for NSCLC." (PMID 33539648, 2021). "Fusions of NRG1, the activating ligand of HER3, are rare genomic alterations found in 0.2%‒0.5% of all solid tumors and have been identified in > 10 unique tumor types." (PMID 34250553, 2021). "Its activation by NRG1 promotes activation of AKT and ERK1/2, contributing to tumour progression and therapy resistance." (PMID 33692466, 2021).
tumor (continued). "A previous study displayed that NRG1 exerted its roles in tumors by binding to ERBB2 or ERBB3, resulting in tumor cell proliferation, invasion, and migration." (PMID 34531912, 2021). "In order to evaluate the security, tolerability and anti-tumor efficacy of MCLA-128, a Phase I/II dose-escalating clinical trial in patients with solid cancers carrying an NRG1 fusion is initiated (NCT02912949)." (PMID 34922633, 2021). "Since the completion of this study, our knowledge of NRG1 fusions and their role in HER3 tumor biology has expanded notably, along with the increasing number of NRG1 fusion partners identified across multiple solid tumor types." (PMID 34250553, 2021). "Inhibition of NRG1‐ and other ligand‐mediated HER4 signalling can consistently and significantly enhance the response to chemotherapy and delay tumour regrowth after cessation of treatment." (PMID 33539648, 2021). "An example of a p63 target in SCC is NRG1, which can be inhibited to block SCC proliferation and tumor growth." (PMID 33263276, 2020). "These authors also noted a significant correlation between rs2439302 genotype and lower expression of NRG1 in normal thyroid and PTC tumor tissue." (PMID 31247975, 2019). "Compared with other tumours, HNSCC have among the highest levels of NRG1, and tumours recurrence further increases neuregulin‐1 expression after curative treatments with radiation and chemotherapy." (PMID 30845357, 2019). "Although most DNA alterations found in patient tumor PH212 were detected in the derivative PDX, the expression of a key player in ERBB signaling pathway, NRG1 was lost in the PDX completely, whereas it was very high in the original tumor." (PMID 30499260, 2019). "Most methylation probes exhibited strong discriminatory performance between tumor and normal tissue, with median AUC of 0.834 and probes within three genes—MEIS2, NRG1, and SRPX—exhibiting sensitivities greater than 90%." (PMID 30917865, 2019). "We show that NRG1 can stimulate the ErbB3 receptor on macrophages in order to induce JAG1 expression, which acts as a ligand for the tumor cell Notch receptor, increasing their capacity for transendothelial migration and intravasation." (PMID 29636067, 2018). "Although lapatinib exhibited anti-tumor activity against BRD4-amplified tumor models, and gave significant combination activity with AZD5153, further investigation will be required to interrogate the role of NRG1 as a therapeutic target." (PMID 30036377, 2018). "We found significant cis-eQTL of genes near NRG1, NKX2-1, DIRC3, PCNXL2 and VAV3 in the normal and tumour thyroid tissue." (PMID 28703219, 2017). "Both mechanisms of HER3 activation can be targeted in a number of different tumor types by LJM716, which displays single-agent antitumor activity in a range of HER2-amplified and NRG1-expressing xenograft models." (PMID 28899363, 2017). "There was only one tumor suppressor (CSF2) and one cancer census gene in Cluster 3 (USP6); there are four tumor suppressors (GALR1, IRF4, PTPRT and SOX11) and one more cancer census gene in Cluster 4 (NRG1)." (PMID 28198667, 2017). "Biomarker subtype analysis was performed for NRG1 and ERBB3 in 108 tumor samples (89%; 51/59 in the duligotuzumab arm and 57/62 in the cetuximab arm), both potential indicators of HER3 activity." (PMID 27843803, 2016). "One sample was NRG1 FISH‐positive and 100% of the tumor nuclei analyzed were positive, harboring at least one isolated orange signal, together with at least 1 fusion signal." (PMID 27770508, 2016). "Proliferation, and tumor volume and weight were analyzed for cancer cells ectopically expressing SLC3A2, NRG1 and SLC3A2-NRG1." (PMID 27626312, 2016). "In this study, we examined methylation patterns of ten tumor-associated genes (RASSF1A, GSTP1, RIZ1, SOCS1, TNFRSF10C, hTERT, NRG1, CLU, miR-203, miR-663) and of the LINE-1 repetitive element in 45 HCC and 17 matching non-tumor livers." (PMID 25889455, 2015).
tumor (continued). "Among those putative target candidates, five potential tumor suppressors, including CCNG2, FOXP1, NRG1, LRIG1, and TNFSF10, were shown to have a direct binding site with miR-130b-5p." (PMID 25888956, 2015). "We analysed mRNA transcript expression levels of EGFR ligands (EGF and TGF-α) and two isoforms of the ErbB3 ligand, NRG-1 (NRG-1α and NRG-1β) in each one of those two tumour compartments." (PMID 21792199, 2011). "Although this suggests that copy number alterations and DNA breakpoints close to NRG1 do not affect expression, this does not preclude the possibility that in some cases downregulated expression (for example, tumours 1–9) may be caused by promoter hypermethylation." (PMID 21364580, 2011). "Notably, NRG1 fusions were identified in a subset of tumours, including recurrent SDC4::NRG1 events, potentially playing key roles in disease progression." (PMID 41914575, 2026). "We found that early DOX exposure induced systolic dysfunction and pathological remodeling, while daily NRG1 preserved the ejection fraction and attenuated structural changes without impairing anti-tumor efficacy." (PMID 42196592, 2026). "It outlines the stringent technical requirements and testing methods necessary to ensure high fidelity to the original tumor tissue, including morphological assessment, pathological biomarker expression (e.g., CK19, CK7), and genetic concordance (e.g., NRG1, KRAS)." (PMID 42026891, 2026). "Currently, there are no FDA-approved targeted therapies specifically for NRG1 fusions, but treatments targeting the NRG1/ErbB signaling pathway have shown both preclinical and clinical efficacy in several tumor types." (PMID 40576713, 2025). "This signaling was not driven by the tumor cells themselves but rather by infiltrating myelomonocytic immune cells, which secrete NRG1 in a paracrine fashion." (PMID 41228234, 2025). "Additionally, hormone deprivation triggered an upregulation of tumor drug resistance genes ABCB11, BIRC3, FGF2 and NRG1." (PMID 40075208, 2025). "This implies that in addition to secreting NRG1, chemokines, and inflammatory factors, STEAP4+ myoCAF may also secrete specific lipids to facilitate tumor cell proliferation and survival under the selective pressure of enzalutamide." (PMID 40917018, 2025). "Using this tool, we investigated DNA methylation-related functional elements and found that 17 CpG sites in both the promoter and non-promoter regions of NRG1 had higher methylation β values in tumor samples compared to normal samples." (PMID 41190067, 2025). "Indeed, NRG1 fusions drive cancer development through aberrant ERBB receptor-mediated signaling, and ERBB inhibition can inhibit the tumor growth of NRG1-rearranged cancers." (PMID 40723230, 2025). "Regardless of the tumor type, the mutation frequencies of CD74, FGFR1, and RET were significantly greater in patients with NRG1 fusion than in patients without NRG1 fusion." (PMID 40730881, 2025). "The analysis result showed that the levels of NRG1 from blood and tumor tissue were significantly higher in CRPC patients than that in NCRPC patients, demonstrating that NRG1 might correlate to CRPC progression." (PMID 40740239, 2025). "By analyzing the ligands corresponding to chemokine target genes expressed in immune cells, we found that the chemotactic response of immune cells was mediated by the expression of NRG1 and HMGB1 ligands on Tum_1 tumor cells, which interacted with the CXCL1 target on APOE+ macrophages." (PMID 40470730, 2025). "Neuregulin 1 (NRG1) gene is a rare oncogenic driver that can lead to activation of human epidermal growth factor receptor 3 (Her3/ErbB3) mediated pathway, resulting in tumor formation." (PMID 38880928, 2024).
tumor (continued). "The comprehensive identification of NRG1 fusions may involve next-generation sequencing (NGS) technologies, both RNA and DNA-based, which allow for high-throughput genomic profiling of tumor samples." (PMID 39123493, 2024). "We identified 42 and 16 TSGs monoallelically deleted in P2 and P5, respectively, including several TSGs deleted in both tumor samples (ARHGEF10, CDKN1B, ETNK1, ETV6, LEPROTL1, NRG1, PTPN6, and WRN) and many TSGs co-deleted in the same subclone as well as across multiple subclones." (PMID 38658552, 2024). "In summary, the involvement of NRG1 in promoting ERBB3-mediated signaling and the formation of oncogenic heterodimers with ERBB1, ERBB2, and ERBB4 highlights the significance of NRG1 fusions in driving abnormal cell proliferation and tumor progression." (PMID 38957319, 2024). "We observed higher protein expression levels of NRG1, determined by immunohistochemistry (IHC), in tumor samples from nonresponders and after radiotherapy treatment." (PMID 37424047, 2023). "Furthermore, there are various tumor types that have been identified as being NRG1-positive, suggesting that HIF1A and NRG1 have pleiotropic effects on OSA and cancer." (PMID 36831404, 2023). "In addition, analysis of 89 HPV( +) and 409 HPV(-) primary HNC tumor samples in the TCGA as well as 33 HNC cell lines in Cancer Cell Line Encyclopedia (CCLE) showed a positive correlation between AXL and NRG1 mRNA levels." (PMID 35461210, 2022). "The fact that NRG1 is the main activating ligand of HER3, suggests that tumours with high levels of NRG1 could respond better to anti-HER3 targeted therapies." (PMID 33692466, 2021). "Other adipocyte-secreted factors have been described to promote tumor cell resistance to TKI, including the tissue inhibitor metalloproteinase-1 (TIMP-1), interleukin-6 (IL-6), the fibroblast growth factor (FGF) and neuregulin-1 (NRG-1)." (PMID 32795383, 2020). "Genome-wide CN analysis of the 13 intrinsic-resistant tumours revealed NRG1 and GNAS amplifications in CRC tumours without any aberrations in RAS/RAF pathway genes." (PMID 31653970, 2019). "It was not possible to obtain specific immunostaining for NRG1 in tumor cells from ascites due to the existence of a high background of cytosolic staining of cells in suspension." (PMID 30499260, 2019). "In summary, NRG1, ITGA3 and MAP1LC3A may serve as tumor inducers by regulating autophagy and apoptosis in GBM." (PMID 31844032, 2019). "In agreement with the role of FGFR1 in promoting cell proliferation and carcinogenesis, a number of iFGFR1-upregulated genes are cancer-driving genes such as ETS1, PIM1, NRG1, MMP1, and FOXQ1, while some iFGFR1-downregulated genes are tumor suppressors such as NR4A1 and GDF15." (PMID 30111373, 2018). "Stimulation of macrophages with NRG1 upregulated mRNA and protein expression of JAG1, a ligand of the Notch receptor, and JAG1 production by macrophages was important for transendothelial migration of tumor cells." (PMID 29636067, 2018). "Altogether, the data suggest that in HNSCC, full EGFR activation is dependent on the ErbB3-neuregulin-1 axis, a hierarchy that has not been previously demonstrated in any tumor type." (PMID 29305574, 2018). "Since NRG1 is expressed in the majority of HNSCC tumors, we asked whether ErbB3 itself is also expressed in HNSCC patient samples and thus, may serve as a tumor target for anticancer therapy." (PMID 28723928, 2017). "We found that ErbB3, HER2 and NRG1 expression are particularly widespread in HNSCC, in agreement with other published studies, and providing a rationale for evaluation of dual ErbB blockage to improve the benefit of cetuximab treatment in this tumor type." (PMID 28723928, 2017). "In conclusion, our data suggest that while necessary, NRG1 positivity alone does not fully predict KTN3379 anti-tumor activity, but its activity was enriched in cell lines that expressed both NRG1 and high levels of AREG or TGFα." (PMID 28723928, 2017).